VEGFA (vascular endothelial growth factor A)
Diseases named in the same sentence as VEGFA in open-access papers (continued):
Sharing a sentence is not in itself a finding about the gene and the disease.
membranoproliferative glomerulonephritis (1 paper, 2020). Inflammation of the glomeruli characterized by deposits at the intraglomerular mesangium, resulting in thickening of the glomerular basement membrane, activation of complement, and impaired kidney function secondary to damaged glomeruli. "In membranoproliferative glomerulonephritis, studies have demonstrated a protective VEGFA up‐regulation for the endothelium, suggesting, again, that in acute setting VEGFA therapy could help to increase capillary repair." (PMID 33067928, 2020).
papillary adenocarcinoma (1 paper, 2017). A morphologic variant of adenocarcinoma. "VEGFA protein expression was detected in 6/13 (~46%) lepidic adenocarcinomas, 3/5 (60%) papillary adenocarcinoma and 9/11 (~81%) normal lungs." (PMID 29137669, 2017). "We did not detect differences in the levels of VEGFA mRNA or proteins between lepidic and papillary adenocarcinomas." (PMID 29137669, 2017).
paranasal sinus squamous cell carcinoma (1 paper, 2024). A squamous cell carcinoma that arises from the mucosal epithelial surface of the ethmoid, frontal, maxillary, or sphenoid sinus. "Overexpression of VEGFA is found to promote the survival and capillar-like tube formation of paranasal Sinus Squamous Cell Carcinoma (SNSCC) cells, and inhibit the apoptosis." (PMID 37925811, 2024).
pelvic inflammatory disease (1 paper, 2020). Pelvic inflammatory disease (PID) is an acute or chronic inflammation in the pelvic cavity. "The key target proteins for the SC and PS against pelvic inflammatory disease with dampness-heat stasis syndrome included vascular endothelial growth factor A (VEGFA), von willebrand factor (VWF), interleukin 6 (IL6), tumor necrosis factor (TNF) and nuclear transcription factor 1 (NFκB1)." (PMID 33424592, 2020).
renal oncocytomas (1 paper, 2008). "Moreover, while up-regulation of HIF-target genes such as VEGFA are associated with the development of clear cell RCC, these results suggest that down-regulation of distinct subset of HIF-target genes are associated with the development of renal oncocytomas." (PMID 18773095, 2008).
scrapie (1 paper, 2014). A fatal disease of the nervous system in sheep and goats, characterized by pruritus, debility, and locomotor incoordination. "The expression of vascular endothelial growth factor (VEGF, also known as VEGFA), which is also involved in angiogenesis, was altered in scrapie." (PMID 24450868, 2014). "As observed for SERPINE1, we detected a slight decrease in VEGFA expression in lymphatic tissues in the preclinical stage of natural scrapie, followed by a moderate increase during the clinical stage of the disease." (PMID 24450868, 2014). "Accordingly, the differential regulation of SERPINE1 and VEGFA observed in scrapie may reflect a role in prion propagation." (PMID 24450868, 2014).
sudden infant death syndrome (1 paper, 2021). Unexpected death in infancy which remains unexplained following autopsy, review of the medical history, and investigation of the death circumstances and death scene. "SS fibroblasts exhibited down-regulation of VEGFA, affecting other WikiPathways (the endothelin, PodNet: protein-protein interactions in the podocyte pathways as well as the PI3K-Akt signaling/focal adhesion-PI3K-Akt-mTOR-signaling and the sudden infant death syndrome (SIDS) Susceptibility pathways." (PMID 33669496, 2021).
T-cell leukemia (1 paper, 2016). A malignant disease of the T-lymphocytes in the bone marrow, thymus, and/or blood. "VEGFA was strongly expressed in ES cells, significantly downregulated in B and T lymphocytes, and reactivated to the ES level in T cell leukemia." (PMID 26886256, 2016).
thymic epithelial tumors (1 paper, 2023). "Elevated serum levels of VEGFA have been observed in thymic epithelial tumor patients, and there is a reported association between VEGF expression and the invasiveness of thymic epithelial tumors." (PMID 38201593, 2023).
tyrosine metabolism disorders (1 paper, 2025). "VSZT increased water excretion and decreased MAE formation to alleviate MAE through regulating gut microbiota, restoring tryptophan and tyrosine metabolism disorders, and affecting cAMP-PKA-CREB-AQP3 and VEGFA-VEGFR2-SRC-VE-cadherine pathway." (PMID 41044610, 2025).
vascular parkinsonism (1 paper, 2024). A Parkinsonism that is characterized by postural instability, a broad-based gait with the absence of tremors of vascular origin. "The genetic markers of vascular parkinsonism suchas TFAM, CASP3, ALBU, and VEGFA have a stronger regulatoryinfluence on acylcarnitine metabolism enzymes, whereasFBX7, NOTC3, and FA12 predominantly affect amino acidmetabolism enzymes." (PMID 39944797, 2024).
Wolfram syndrome (1 paper, 2022). Wolfram syndrome (WS) also known as DIDMOAD, is a neurodegenerative disorder characterized by type I diabetes mellitus (DM), diabetes insipidus (DI), sensorineural deafness (D), bilateral optical atrophy (OA) and neurological signs. "WFS1-deficient cells are vulnerable to ER stress, which promotes VegfA expression, which may lead to hypervascularization and macrophage infiltration in the Wolfram syndrome model mice islets." (PMID 35399956, 2022).
tumor (17,495 papers, 1997 to 2026). "The persistent upregulation of VEGFA across models further substantiates the onset of an angiogenic angiogenesis, a hallmark of early tumour progression and a key feature of TNBC aggressiveness." (PMID 41579217, 2026). "Functionally, METTL14 depletion promoted HUVEC tube formation in vitro and augmented tumor angiogenesis in vivo, effects mechanistically linked to VEGFA upregulation." (PMID 42213490, 2026). "ccRCC is often characterized by inactivating mutations in the VHL gene, which lead to HIFα-mediated VEGFA production and the development of highly vascularized tumours." (PMID 40435846, 2025). "Recent multi-omics profiling revealed that histone lactylation (notably H3K18la, H4K12la) upregulates ARG1, VEGFA, and M2 macrophage–associated genes, thereby promoting immunosuppressive polarization in the tumor microenvironment." (PMID 41583433, 2025). "PAK1KD inhibited tumour growth and was associated with reducing VEGFA-driven angiogenesis, promoting vascular normalisation and stromal or vascular changes associated with ICAM-1 expression, and reducing hypoxia." (PMID 41294859, 2025). "Elevated VEGFA levels in GBM are associated with increased tumor vascularization, which contributes to tumor growth and resistance to treatment." (PMID 41275376, 2025). "This functional dichotomy aligns with the known activities of these mediators: where TNF supports cytotoxic immune responses associated with anti-tumor effects, VEGFA is related to angiogenesis." (PMID 41465542, 2025). "The compression stress associated with tumour growth can induce angiogenesis either by directly overexpressing vascular endothelial growth factor A (VEGFA) secretion or, indirectly, by blocking existing blood vessels to promote hypoxia and VEGFA secretion." (PMID 39917412, 2025). "In tumor models, VEGFA has been associated with enhanced YAP/TAZ activation via receptor-mediated signaling, contributing to angiogenic switching and tissue invasion." (PMID 40725084, 2025). "The expression of EphA2 and vascular endothelial growth factor A (VEGFA) are closely linked to tumor metastasis." (PMID 39802639, 2025). "In the high-risk state, the expression levels of VEGFA were significantly increased in Macrophages, Mast cells, Monocytes and tumor cells; FLT1 and KDR were significantly increased in Endothelial; and PGF was significantly increased in Mesangial." (PMID 40563096, 2025). "Although the deletion of tumor VEGFA in DKO tumors restored CAR T susceptibility and extended survival, the response was incomplete; after an initial remission, DKO tumors relapsed." (PMID 39998425, 2025). "An SPP1+/VSIG4+ tumour-associated-macrophage programme, transcriptionally linked to angiogenic VEGFA and epithelial–mesenchymal transition, coincides with radio-iodine refractoriness and predicts failure of PD-1 monotherapy." (PMID 40959084, 2025). "Tumor progression is frequently linked to enhanced angiogenesis, with VEGFA playing a central role in this process." (PMID 40141978, 2025). "Elevated VEGFA levels typically correspond to accelerated tumor progression, an increased risk of recurrence, and reduced overall survival." (PMID 40726441, 2025). "Like the CSC markers, 5FU also caused the increase in HIF1α and VEGFA expression within the tumor niche." (PMID 40045186, 2025). "The VCAN G3 domain is implicated directly in angiogenesis, with tumor cells expressing a G3 construct showing increased expression of fibronectin and VEGFA, and the ability to increase EC proliferation and migration." (PMID 40623650, 2025). "In contrast, in the primary tumors, VEGFA was positively associated with endothelial cells and neutrophils, and negatively with NK cells, highlighting tumor stage-specific immune interactions." (PMID 40943183, 2025).
tumor (continued). "VEGFA is a well-known cytokine that promotes angiogenesis and vascular permeability and has been implicated in creating an immunosuppressive tumor microenvironment by inhibiting the function of immune cells, such as T cells and dendritic cells." (PMID 41049442, 2025). "Accumulating evidence demonstrates that VEGFA overexpression is closely associated with enhanced tumor aggressiveness, a greater likelihood of metastasis, and unfavorable clinical outcomes, making VEGFA a valuable biomarker for predicting patient prognosis." (PMID 40726441, 2025). "In particular, HIF1α was shown to promote tumor-associated vascular remodeling by up-regulating the expression of target genes involved in angiogenesis, including VEGFA and matrix metalloproteinases (MMP)." (PMID 39953610, 2025). "Liu and colleagues identified three CAF subtypes (HLA-DRB1, MMP11, and VEGFA), with VEGFA+ CAFs activated by the hypoxic microenvironment, linked to poorer prognosis, and promoting tumor angiogenesis through interactions with capillary endothelial cells." (PMID 40755769, 2025). "TAMs contribute to angiogenesis by activating and releasing these factors, and TAM-derived VEGFA plays a crucial role in driving tumor-associated angiogenesis." (PMID 40041495, 2025). "GPR65 deficiency increased vascular endothelial growth factor A (VEGFA) production in tumor cells, which expanded macrophages and skewed them toward an M2-like immunosuppressive phenotype." (PMID 41152975, 2025). "The recruitment of other immune cells, including tumor-associated macrophages (TAMs), can support tumor angiogenesis by releasing VEGFA and metalloproteinases, which break down the extracellular matrix and release pro-angiogenic factors sequestered on the ECM." (PMID 39567756, 2025). "In the tumor ecosystem, the biological functions of VEGFA and VEGFC are primarily linked to tumor angiogenesis and lymphangiogenesis." (PMID 40843133, 2025). "VEGFA also suppresses immunity by modulating dendritic cells, myeloid-derived suppressor cells, and tumor-associated macrophages, promoting regulatory T-cell accumulation and T-cell suppression, facilitating immune escape." (PMID 40173050, 2025). "The protein encoded by VEGFA can induce migration and invasion of vascular endothelial cells, which is crucial for tumor angiogenesis and metastasis." (PMID 38086608, 2024). "Recent studies also highlighted the critical role of cancer-associated fibroblasts in driving tumor angiogenesis by secreting chemokines and VEGFA." (PMID 39190192, 2024). "WNT7B promotes the angiogenic switch and vascular remodeling by increasing VEGFA expression on tumor-associated ECs." (PMID 38426109, 2024). "The close association between elevated VEGFA levels and increased tumor invasiveness, angiogenesis, metastasis, recurrence, and poor prognosis makes VEGFA a promising target for anti‐cancer therapies." (PMID 39606802, 2024). "Gain‐ and loss‐of‐function assays revealed its role as a tumor promoter by promoting immune evasion and angiogenesis by PD‐L1 and VEGFA in HCC." (PMID 38247171, 2024). "In particular, VEGFA production by BC cells induces the differentiation of tumor-associated macrophages toward a pro-angiogenic phenotype." (PMID 38321003, 2024). "The underlying mechanisms of PHF5A and VEGFA would require more related studies to unravel the tumor-promoting details." (PMID 38429756, 2024). "Here, we report that M2-type tumor-associated macrophages (TAMs) contribute to cancer stemness in TNBC cells via the secretion of VEGFA." (PMID 38169627, 2024). "SPP1 + TAMs were characterized by increased expression of SPP1, macrophage receptor with collagenous structure (MARCO), and vascular endothelial growth factor A (VEGFA) and were associated with tumor angiogenesis." (PMID 38443595, 2024). "VEGFA is highly expressed in most human tumors and is closely associated with tumor invasiveness, vascular density, metastasis, recurrence, and prognosis." (PMID 39606802, 2024).
tumor (continued). "Angiogenesis under different conditions, including tumor pathogenesis, is regulated by VEGF, a gene family that includes several VEGF variants such as VEGFA, B, C and D, alongside placental growth factor (PGF)." (PMID 38816668, 2024). "VEGFA secreted from colorectal carcinoma cells activated CXCL1 production in tumor-associated macrophages, which recruited CXCR2-positive MDSCs to form a pre-metastatic niche that ultimately promoted liver metastases." (PMID 38687357, 2024). "Cancer cells have been shown to actively secrete pro-angiogenic growth factors such as vascular endothelial growth factor A (VEGFA) to promote tumour-associated angiogenesis." (PMID 38256941, 2024). "This prompts the question: why do tumor cells, bathed in high VEGFA concentrations and theoretically susceptible to bevacizumab, seemingly resist its direct cytotoxic effects?" (PMID 38716237, 2024). "Considering that CXCL12 attracts infiltration of tumor-associated macrophages (TAMs), which are a significant source of VEGFA and vital chemoattractant for macrophages." (PMID 38611849, 2024). "C-X-C chemokines, by activating the CXCR2, in addition to VEGFA, have been implicated in facilitating tumor angiogenesis." (PMID 38515019, 2024). "Mechanistically, SNHG11 acts as a ceRNA for miR‐324‐3p, therefore upregulating VEGFA, which has previously been implicated in tumour angiogenesis." (PMID 38341827, 2024). "The expression of vascular endothelial growth factor A (VEGF-A), a marker of angiogenic activity, is known to be increased in PCa and associated with poorer prognosis, distant metastasis and advanced tumor grading." (PMID 37090711, 2023). "We further investigated the association between VEGFA/CTNNB1/MMP7/CD44 oncogenic expressions with selected immune cells in the tumor microenvironment (TME)." (PMID 36672201, 2023). "Upon reviewing the literature, we noticed that AURKA was closely associated with tumor angiogenesis with positive effect on VEGFA transcription and glucose metabolism." (PMID 36977984, 2023). "Loss of FBXW7 promoted tumor proliferation, invasion and migration ability via VEGFA and MMP3 activation through ERK phosphorylation." (PMID 36991467, 2023). "MiR-29b causes negative regulation of angiogenesis and tumor growth in EC by downregulating vascular endothelial growth factor A (VEGFA) via deactivation of the MAPK/ERK and PI3K/AKT pathways." (PMID 37663424, 2023). "VEGFA alters the process of antigen presentation by impairing the maturation of DCs and inducing PD-L1 expression in tumor-associated myeloid DCs." (PMID 37190304, 2023). "VEGFA activation and subsequent tumor metastasis are tightly linked to three key MAPK signaling pathways: p38, ERK1/2, and JNK." (PMID 38104099, 2023). "A study evaluating tumor tissues from patients treated with bevacizumab plus irinotecan showed that high VEGFA expression was associated with higher probability of response to radiotherapy." (PMID 37190125, 2023). "The production of growth factors such as vascular endothelial growth factor A (VEGF-A) by tumor-associated macrophages encourages tumor invasion by using various mechanisms, such as inducing angiogenesis." (PMID 36831661, 2023). "Considering that higher expression of VEGFA is mostly associated with more advanced‐stage tumours and that advanced‐stage tumours often lose the opportunity for surgery, VEGFA is a good therapeutic target for these patients." (PMID 36729917, 2023). "Our analysis identified CX3CR1+ monocytes as associated with anti-tumor activity, and another immunosuppressive VEGFA+ monocytes as associated with poor response." (PMID 36869384, 2023). "VEGFA is distributed in almost all cell types of tumor tissues, such as cancer cells, tumor-associated macrophages and endothelial cells, implying its broad role in cancer development." (PMID 37234708, 2023).